ALB (albumin)
Diseases named in the same sentence as ALB in open-access papers (continued):
Sharing a sentence is not in itself a finding about the gene and the disease.
tumor (continued). "Additionally, a preoperative and postoperative ERASL model based on gender, albumin, AFP, and tumor size and number categorized the risk of HCC recurrence into high, intermediate, and low groups." (PMID 39816698, 2025). "Univariate analysis identified the following variables as significant predictors of OS: NLR (p < 0.001), PLR (p = 0.001), MLR (p < 0.001), SII (p < 0.001), PIV (p < 0.001), CRP (p < 0.001), LDH (p = 0.043), albumin (p = 0.001), tumor size (p = 0.001), and ECOG PS (p < 0.001)." (PMID 39851955, 2025). "Each operates via distinct mechanisms: 5-ALA is metabolized by tumor cells into fluorescent protoporphyrin IX; SF binds to serum albumin, which accumulates around the tumor due to damage to the blood–brain barrier (BBB); and ICG primarily binds to plasma proteins in the bloodstream." (PMID 40867331, 2025). "Albumin-bound paclitaxel improves solubility, bioavailability, and tumor-specific accumulation." (PMID 39861768, 2025). "Previous studies have revealed that tumor cells can produce and release some inflammatory mediators, such as tumor necrosis factor-alpha and interleukin-6, which may inhibit the synthesis of albumin in the liver, potentially resulting in hypoproteinemia." (PMID 40265018, 2025). "In contrast, tumor volume showed a negative association with albumin levels (r = −0.45, p = 0.007) and the albumin/D-dimer ratio (r = −0.46, p = 0.03)." (PMID 40283046, 2025). "Chitosan, a polysaccharide derived from crustacean shells, exhibits enhanced epithelial permeability and immunogenic properties, while albumin, owing to its human origin, provides prolonged circulation time and accumulation within the abnormal tumor vasculature." (PMID 40390104, 2025). "Here, we investigated how hepatocyte TM4SF5 could modulate extracellular ALB uptake, leading to sufficient ATP synthesis for tumor progression." (PMID 40186033, 2025). "However, all graphs showed a trend towards an increase in percent change when non-tumour absorbed doses increased, except for albumin where an inverse relationship was observed." (PMID 39470786, 2025). "The domains binding a tumor antigen and albumin typically are single-domain antibodies (VHH)." (PMID 40416957, 2025). "Furthermore, an evaluation of gene expression related to normal liver marker ALB demonstrated markedly heightened expression of ALB in normal epithelial cells, indicating that the tumor tissue has lost its normal function." (PMID 39950116, 2025). "The data analysis revealed that among the 2 groups of patients being compared, there were no significant statistical differences in factors such as gender, age, PS, smoking status, albumin, tumor differentiation, metastatic site, tumor markers, and chemotherapy (all P > .05)." (PMID 41305823, 2025). "The cut-off values for predicting OS were determined based on the areas under the curve (AUC) in the ROC analyses, as follows: D-dimer—0.55 μg/mL; albumin—4.3 g/dL; albumin/D-dimer ratio—6.5; PT—12.53 s; aPTT—23 s; platelet count—313 × 103; and tumor volume—36.3 cm3." (PMID 40283046, 2025). "The SII-PNI score demonstrates good predictive value for pCR and prognostic stratification, and its underlying mechanism may involve the roles of LYM, ALB, NEU, and PLT in tumor progression." (PMID 41357195, 2025). "Furthermore, recent investigations into pan-immune-inflammatory values and the albumin-to-globulin ratio in CRC highlight the superior prognostic power achieved by integrating tumor markers with immune-inflammatory indicators." (PMID 41216199, 2025). "Dysregulated albumin levels may promote colorectal carcinogenesis by disrupting redox balance and immune function, while tumor progression itself can further deplete systemic albumin." (PMID 41299673, 2025). "Many studies have confirmed the potential of albumin to deliver drugs to tumor tissues." (PMID 38255859, 2024). "Consequently, curcumin is the most studied phenolic compound in the field of anti-tumor albumin NPs in oncology." (PMID 39070787, 2024).
tumor (continued). "Binding to albumin leads to a prolonged circulation of the radiotracer in the blood pool and, thus, to an increased area under the curve and, additionally, to increased tumor-to-kidney ratios in radiotherapeutic applications." (PMID 39661209, 2024). "Furthermore, this protocol is a reliable option for the search of potential tumour cell membrane markers, as only secreted proteins were reduced along with the most abundant glycoproteins, albumin and immunoglobulins." (PMID 38750435, 2024). "Thus, it was related to the prediction that the occurrence of CKD after surgery would be higher when the eGFR value was lower, albumin was lower, tumor size was larger, calcium level was lower, creatinine level was lower, and Hb level was higher." (PMID 38519947, 2024). "Body mass index, preoperative hemoglobin, preoperative albumin, preoperative carcinoma embryonic antigen, tumor location, neoadjuvant chemoradiotherapy, smoking, history of abdominal surgery, and open surgery did not significantly change the risk of TI non-closure." (PMID 38610000, 2024). "However, it presents technical challenges and relies on technetium-99m macroaggregated albumin (Tc-MAA) as a surrogate for microsphere distribution in the tumor." (PMID 38392039, 2024). "Patients who had the following factors including male, the number of comorbidities was ≥2, postoperative serum albumin <35 g/L, tumor location was EGJ, duration of operation ≥260 min were more likely to develop EJAL than those who had not (p = 0.023, 0.036, 0.032, 0.016, 0.004 respectively)." (PMID 39669366, 2024). "Albumin‐based nanocarriers could potentially overcome cancer drug resistance through bypassing drug efflux, enhancing drug uptake, and improving tumor accumulation." (PMID 39434967, 2024). "Low albumin levels or poor nutritional status could lead to impaired immune function in tumor patients and promote tumor proliferation, invasion, and migration." (PMID 38978733, 2024). "The screened variables included age, BCLC stage, tumor size, ALB, Palb, GLB, GGT, and bile acids." (PMID 38601167, 2024). "However, individual markers such as CRP, LDH, and albumin are influenced by a variety of non-tumor-related factors, resulting in low specificity." (PMID 39796668, 2024). "Other stratification factors were used in literature: performance status, primary tumor localization (head vs body or tail), albumin, time since receiving most recent anticancer therapy, tumor stage at diagnosis, baseline CA19-9 number of metastatic sites, peritoneal carcinomatosis, CRP>5mg/dL." (PMID 38408958, 2024). "Simultaneously, tumor cells may release cytokines, such as IL-6, which impede the formation of albumin in hepatocytes." (PMID 38169970, 2024). "Hence, combining both makers to form the AAPR has been shown to be a more accurate indicator of tumor behavior than albumin or alkaline phosphatase alone." (PMID 39596952, 2024). "What is more, a systemic inflammation response to the tumor inhibits albumin synthesis." (PMID 39272712, 2024). "Notably, Desai N was involved in the development and application of Abraxane® and Fyarro®, which are the only two albumin-bound anti-tumor drugs used in clinic." (PMID 39070787, 2024). "Interpretability assessments using SHAP values indicated that the most significant characteristic risk factors, in descending order of importance, were tumor number, BCLC stage, alkaline phosphatase (ALP), ascites, albumin (ALB), and aspartate aminotransferase (AST)." (PMID 39372198, 2024). "Notably, only two albumin-bound anti-tumor drugs have been launched since the introduction of Abraxane® in 2005 (generic versions of Abraxane® from different countries are not included)." (PMID 39070787, 2024). "Additionally, there were significant differences between the two groups in L3-SMI, muscle attenuation, maximal tumor diameter, albumin, creatinine, albumin to globulin ratio (AAR), platelet to lymphocyte ratio (PLR), and neutrophil to lymphocyte ratio (NLR)." (PMID 38434977, 2024).
tumor (continued). "The results of univariate analysis showed that the FAR (p < 0.001), FLR (p < 0.001), FHR (p = 0.003), APAR (p < 0.001), albumin (p = 0.008), FBG, AJCC stage (p < 0.001), histological grade (p = 0.002), and tumor diameter (p = 0.048) were significantly associated with PFS." (PMID 39064013, 2024). "Moderate strength relationships were observed between weight loss and tumor size (ρ = −0.461, p < 0.001), tumor DOI (ρ = −0.321, p < 0.001), and serum albumin (ρ = −0.310, p < 0.001), while weak associations were seen with nodal disease (ρ = 0.222, p < 0.001) and Hgb (ρ = −0.197, p=0.005)." (PMID 38966634, 2024). "Treatment effects on tumor growth, leukocyte numbers, and renal albumin excretion were assessed." (PMID 39310112, 2024). "Therefore, small-molecular-weight molecules have been modified with albumin binders to enhance their blood circulation time and, hence, increase the tumor uptake." (PMID 38610940, 2024). "The key laboratory values assessed during this phase include alkaline phosphatase (AP), glutamate oxaloacetate transaminase (GOT), glutamate–pyruvate transaminase (GPT), gamma-glutamyl transferase (GGT), albumin, total bilirubin, and tumor markers CA 19-9, CEA, and AFP (alpha-fetoprotein)." (PMID 39796681, 2024). "It is believed that the albumin-mediated delivery of nab-paclitaxel may enhance its transportation to tumours, improve tolerability, reduce infusion time, and eliminate the need for preoperative prophylactic medication." (PMID 39234401, 2024). "The entry of legubicin into the circulation as an albumin conjugate and its specific activation by legumain in the tumor microenvironment may significantly modify its pharmacokinetic and tissue distribution behavior in vivo, compared to doxorubicin." (PMID 38398527, 2024). "ASGPR1-positive and -negative exosomes should be sorted and analyzed for the expression of other HCC-specific genes, including Albumin and α-fetoprotein, thereby aiding in establishing the robustness of the membrane marker in identifying exosomes released from the tumor." (PMID 39766289, 2024). "In addition to tumour-specific antibodies and peptides, the possibility of using serum albumin-based nanoparticles for targeted imaging of certain tumours is being studied." (PMID 39337680, 2024). "We further demonstrate the programmability of the platform for integrating tumor targeting and additional immunoregulatory functions through the development of a bispecific nanobody-diABZI conjugate that binds to both albumin and the immune checkpoint ligand PD-L1." (PMID 38766114, 2024). "Moreover, the design of dual-peptide-functionalized albumin-based nanoparticles has demonstrated efficient tumor-targeted drug delivery in GBM cells." (PMID 39272576, 2024). "Given that 98.6% of LD4172 is bound to plasma proteins, it is plausible that LD4172 may be “piggybacking” on albumin accumulation in tumors, thereby achieving tumor-selective RIPK1 degradation." (PMID 39681571, 2024). "Accordingly, the co-loading of paclitaxel and curcumin in albumin NPs may exert their combined anti-tumor effect and reduce the side effects of paclitaxel." (PMID 39070787, 2024). "Albumin-decorated NLC-I and II-SambucusN ensured a certain intensity of the apoptosis process that caused the death of tumour cells in a high percentage, i.e., 50 μg/mL of NLC-II-SambucusN-BSA induced over 50% apoptosis in Lovo colon cells, 4 times higher compared to the untreated cells." (PMID 39456987, 2024). "The score for complications is calculated based on six key parameters that indicate the risk factors for complications: hemoglobin (Hb) levels, preoperative serum albumin, tumor localization, the presence of an epidural catheter (EC), opioid use, and the duration of NPO (nil per os) status." (PMID 39845228, 2024). "Consequently, the albumin can serve as a tumor-targeting carrier for enhanced tumor accumulation of BSQ, enabling tumor-targeted imaging and effective PDT." (PMID 38542401, 2024).
tumor (continued). "Albumin accumulates in the tumor interstitium in numerous solid cancer models." (PMID 38383524, 2024). "The hypothesis that albumin neo-structures generated in cancer might have an IL-6-inducing activity was analyzed by incubating tumor homogenates with albumin." (PMID 39518029, 2024). "Preoperative levels of albumin and hemoglobin are also vital for tumor cell immune responses." (PMID 39664192, 2024). "The nomogram integrated four independent risk factors: PNI, Albumin, ASA, and Tumor diameter." (PMID 39568563, 2024). "In addition, exploiting the binding to endogenous human serum albumin (HSA) is a valuable option to achieve tumor targeting and improve the pharmacokinetic profile of drugs and nanosystems." (PMID 38591056, 2024). "Albumin nanoparticles can be enriched in tumor tissue in two ways." (PMID 38323081, 2024). "Our univariable Cox analysis revealed that ALB < 35 g/L, AFP ≥ 200 ng/mL, Child-Pugh B, BCLC A, larger tumor diameter, MVI, Edmondson-Steiner III-IV, NAR, and surgical margin < 1 cm were significantly associated with tumor recurrence (all P < 0.05)." (PMID 39090609, 2024). "Furthermore, albumin-based contrast agents can specifically accumulate in tumour regions by the enhanced permeability and retention (EPR) effect." (PMID 38298593, 2024). "Numerous studies have shown that albumin plays an inhibitory role in the systemic inflammatory response and may contribute to tumor progression." (PMID 38750370, 2024). "Albumin also plays a pivotal role in stabilizing chemokines and cytokines that attract immune cells to the tumor site, and insufficient levels may impede the efficacy of immunotherapy." (PMID 38755213, 2024). "Moreover, the tumor-specific uptake of exogenous albumin can be explained by receptor-mediated albumin uptake pathways related to albumin binding proteins such as membrane-associated glycoprotein and secreted protein acidic and rich in cysteine (SPARC)." (PMID 38791347, 2024). "Besides utilizing glutamine metabolism, tumor cells adapt by scavenging alternative nutrients including lactate or albumin to sustain their metabolism, when glucose becomes scarce." (PMID 39479443, 2024). "Albumin can also be internalized by cancer and tumor-associated immune cell populations through non-receptor-mediated micropinocytosis." (PMID 38766114, 2024). "The mechanism by which SII/ALB might affect prognostic factors can be discussed from the following perspectives: First, neutrophils promote tumor development by directly interacting with tumor cells or indirectly remodeling the tumor microenvironment." (PMID 38935663, 2024). "It was demonstrated that proinflammatory cytokines released by tumor tissue and related inflammatory cells, such as IL-4 and IL-6, could affect the synthesis of albumin in hepatocytes, thus decreasing albumin levels." (PMID 39440062, 2024). "Thus, this system represents an interestingselectivity manifold in which tripartitite tissuoselectivities areexploited: tumor via mAb and blood via albumin circulation (and areduced ability to diffuse from vasculature)." (PMID 38231473, 2024). "The nucleophilic substitution of meso-Cl with water-soluble amino acids or targeting peptides for IP-engineered dye further addresses the nonspecific signals caused by albumin, allowing for adjustable angiography time and efficient tumor targeting." (PMID 38773981, 2024). "Notably, only two albumin-bound anti-tumor drugs are currently available worldwide—Abraxane® and Fyarro®—both of which are prepared using NabTM technology." (PMID 39070787, 2024). "Therefore, Desai N is a pioneer in the application of albumin-based anti-tumor nanomedicine to clinical practice." (PMID 39070787, 2024).
tumor (continued). "Furthermore, it highlighted the potential of albumin NPs in targeted drug delivery to specific tumor sites." (PMID 39070787, 2024). "Unlike free drugs, chemotherapy drugs, immune adjuvants, and photosensitizers can be loaded into the same NP through the albumin multifunctional nanoplatform and enter the tumor tissue at the same time, enabling a variety of treatments to be performed simultaneously or in sequence." (PMID 39070787, 2024). "The meso-Cl was not used due to its tumor-homing properties, as its binding to albumin could enhance its population within the tumor site." (PMID 39518106, 2024). "Notably, high IL-6 levels correlated with adverse features such as poorly differentiated histology, higher tumor burden, and low albumin levels, indicating a stronger likelihood of poorer prognosis." (PMID 38672257, 2024). "All tumor-bearing mice showed significantly lower levels of serum albumin than the NT group." (PMID 39273055, 2024). "Thus, the coating of albumin nanoparticles should be modified in order to prolong their circulation time and favour the chance of tumour arrival." (PMID 39455507, 2024). "Furthermore, positivity was significantly higher in patients who were older, male, had higher cN stage, higher cStage, tumor in upper location, differentiated histological type, and lower albumin levels." (PMID 38455491, 2024). "n501–αHSA–MMAE can bind albumin and possibly accumulate in tumor with the help of albumin." (PMID 38737471, 2024). "Considering the numerous advantages of albumin NPs as drug carriers, including biodegradability, biocompatibility, non-immunogenicity, and long half-life, as well as the successful launch of Abraxane® and Fyarro®, albumin NPs hold great promise in the targeted delivery of anti-tumor drugs." (PMID 39070787, 2024). "Certain inflammatory cytokines can inhibit the synthesis of albumin, and oxidative stress during tumor progression may lead to albumin denaturation." (PMID 39080372, 2024). "Thus, serum albumin ≤ 3.8 g/dL, PT ≤ 80%, and largest tumor diameter ≥ 3.8 cm appeared to be factors related to deterioration in the Child‐Pugh class." (PMID 39487694, 2024). "In contrast, the results of the analysis showed that there was an increase in protein levels after treatment in both tumour groups, with significantly higher levels of prealbumin and albumin in the hematological malignancies and significantly higher levels of albumin in the solid tumour group." (PMID 39619813, 2024). "Additionally, CRP, when combined with albumin levels, erythrocyte sedimentation rate, neutrophil‐to‐lymphocyte ratios, and other factors, has been widely employed to predict tumor prognosis." (PMID 38923354, 2024). "The potency (i.e. EC50 for degranulation and tumor lysis) of the EGFR-Vδ2hi-lo bsVHH-albumin construct was ~10 fold lower compared to the EGFR-Vδ2hi-lo bsVHH-Fc perhaps as a result of impaired immune synapse formation when albumin was bound to the engager in this specific orientation." (PMID 39493452, 2024). "Because tumor penetration ability is inversely proportional to nanoparticle size, polymeric micellar paclitaxel (about 20 nm) was reported to penetrate tumor cells easier and faster than nanoparticle albumin-bound paclitaxel (130 nm)." (PMID 38668776, 2024). "Moreover, albumin exhibits tumor-targeting capacity as it can bind to receptors overexpressed in tumor tissues, such as the cysteine-rich acidic secretory protein (SPARC) and gp60." (PMID 39598513, 2024). "New anti-tumor drugs based on albumin nanotechnology in clinical trials." (PMID 39070787, 2024). "Additionally, the high demand for albumin in tumour tissues further facilitates the concentration of drug-loaded albumin NPs at the tumour site." (PMID 39548502, 2024). "In addition, Albumin <2.5 mg/dL, the presence of neoplasm, and the need for dialysis in the acute phase, calorie adequacy <0.7 in the late phase (HR, 2.19) were identified as additional risk factors." (PMID 39403394, 2024).